DDX5 (DEAD-box helicase 5)
Diseases named in the same sentence as DDX5 in open-access papers (continued):
Sharing a sentence is not in itself a finding about the gene and the disease.
tumor (continued). "We noticed that different DDX5 KO PDAC cell clones exhibited different tumour formation abilities." (PMID 35604033, 2022). "In addition, DDX5 was reported to be abnormally expressed in a variety of tumours and to play a crucial role in tumour progression." (PMID 36347834, 2022). "Next, we investigated whether the modulation of DDX5 expression could affect tumour cell growth and sensitivity to FL118 treatment." (PMID 35604033, 2022). "Studies relevant to SCC also support the idea that DDX5 is important for tumor proliferation." (PMID 35954483, 2022). "DDX17 and DDX5 may play a critical role in tumor cell migration by simultaneously regulating the transcriptional activity and AS of NFAT5 in HeLa cells." (PMID 36164607, 2022). "Additionally, we also observed that the same DDX5 KO clone can exhibit different tumour growth rates." (PMID 35604033, 2022). "As for DDX3X, several DDX5 unique interactors were associated with different tumor types, but again there was a lack of information about the functional significance of these interactions." (PMID 35954483, 2022). "Therefore, DDX5/DDX17 play a key role in tumor cell migration through the fine regulation of the NFAT5 pathway." (PMID 35992805, 2022). "In addition, DDX5/DDX17 interact with important tumor signaling molecules, and DDX5 is involved in DNA repair, oxidative stress, autophagy, and energy metabolism." (PMID 35992805, 2022). "Previous studies have reported that the downregulation of DDX5 inhibits tumor proliferation." (PMID 36313454, 2022). "However, while DDX5 acts as an oncogene, thus presumably enhancing the tumor transformation function of MATR3, DDX3X can act both as an oncogene and as an oncosuppressor." (PMID 35954483, 2022). "Similarly, the data from the Human Protein Atlas Database also documented that DDX5 expression enhances in all 11 CRC tumours (high: 5; medium: 6; low: 0)." (PMID 35604033, 2022). "Furthermore, the in vivo results derived from DDX5 KO PDAC cell tumour formation and growth provided important mechanistic and treatment outcome predictive information." (PMID 35604033, 2022). "Genetic manipulation of DDX5 in PDAC cells affects tumour growth." (PMID 35604033, 2022). "It was also found that the oncogenic lncRNA CCAT1 promotes PC cell proliferation and tumor growth of PC xenotransplantation, acting as a scaffold for the DDX5 and AR transcriptional complex to facilitate the expression of AR-regulated genes in nuclei, thus stimulating PC progression." (PMID 35954483, 2022). "Our studies indicated that DDX5 KO cells significantly delayed tumour formation and growth." (PMID 35604033, 2022). "Ddx5 was increased in the whole skin lesions of MC903- or IMQ-treated Cd93–/– mice compared with their wild-type counterparts, along with fewer plaques on the ears or dorsal skin and reduced expression of Il4, Il13, Ccl11, Ccl17 and Ccl22 or Cxcl1, Cxcl2, Ccl20, Il23, Il17a and Il36γ." (PMID 36271146, 2022). "In contrast, DDX5 mRNA expression in this cohort was also lower than tumor tissues (P = 0.008)." (PMID 33764710, 2021). "A key observation in our study on the prognostic role of DDX5 protein is that a low expression of DDX5 inhibited the malignant phenotype using in vivo tumor growth in the murine HCC xenograft model, leading to a good prognostic outcome after hepatic resection in patients with HCC." (PMID 33764710, 2021). "Here, we demonstrated that knocking out DDX5 in IECs in two models resulted in lower tumor counts." (PMID 32817263, 2020). "However, the expression of DDX5 in the human HCC tumor tissues is relatively lower when compared to its non-tumor counterpart." (PMID 30695997, 2019). "Finally, we examined whether DDX5 enhances endogenous deregulated E2F activity, generated by adenoviral E1a inactivation of RB family members, which activates endogenous tumor suppressor genes." (PMID 39769018, 2024).
tumor (continued). "Indeed, low DDX5 expression correlated with a poor prognosis in patients after tumor resection." (PMID 35954483, 2022). "However, it is unclear whether the resolvase activity of DDX5 on R-loops exerts oncogenic or tumor suppressive effects; this question will be an interesting topic for further investigation." (PMID 35992805, 2022). "Not unexpectedly, alterations in DDX5 metabolism are linked to tumorigenesis, even though the mechanisms underlying the DDX5 oncogenic role may differ from one type of tumor to another and, in some tumors, are not fully characterized." (PMID 35954483, 2022). "Thus, it is possible that DDX5 might mediate the association of SBDS with PP2A, leading to its inhibition and promoting tumor progression in myeloid leukemia cells." (PMID 35954483, 2022). "Additionally, the same DDX5 KO clone can also exhibit different tumour growth rates." (PMID 35604033, 2022). "In our PPI analysis, the majority of the genes in the most closely connected module were significantly upregulated in M1 macrophages, including STAT1, OAS1, OAS2 and DDX5; thus, developing small molecule agonists for these proteins may enhance anti-tumor immunity." (PMID 33323552, 2020). "Interestingly, tumors that escaped DDX5 regulation had comparable size as those found in WT animals on day 120, indicating that DDX5 plays a more critical role during tumor initiation and that other regulators can compensate for its loss at the later phase of tumor growth in vivo." (PMID 32817263, 2020). "Analysis of TCGA database (accession number: phs000178) revealed increased PSI values for ACTA2, AREG, BRCA1, DDX5, MSH6, and PARP1 in tumor tissues compared to adjacent tissues." (PMID 39773744, 2025). "DDX5 is significantly upregulated in ARMS and supports tumor cell proliferation and survival both in vitro and in vivo, partly through its interaction with the histone methyltransferase EHMT2." (PMID 40950397, 2025). "For example, DDX3, DDX5 and DDX17 act as oncogenes or tumor-suppressors in a context-dependent manner." (PMID 38939334, 2024). "In our study, MA inhibited DDX5 expression in HepG2 and A431 cells and enhanced the inhibitory effect of DOX on DDX5 expression in tumor cells." (PMID 39494326, 2024). "Significantly, overexpression of DDX5 in HCC xenografts repressed DVL1 expression and increased ferroptosis, resulting in reduced tumor growth by sorafenib." (PMID 38036507, 2023). "The phosphorylation of DDX5 at residues Y593 and Y595 inhibits TRAIL-induced apoptosis and promotes tumor cell proliferation, metastases, and epithelial–mesenchymal transition (EMT)." (PMID 38136426, 2023). "In summary, DDX5 and DDX17 regulate tumorigenesis and tumor progression by participating in RNA metabolism, regulating posttranslational modifications, acting on tumor-related signaling pathways, etc." (PMID 35992805, 2022). "Together, the in vivo data from both PDAC and CRC tumours strongly support that the FL118's target, DDX5, can act as a biomarker and target for predicting PDAC and CRC tumour sensitivity to FL118 treatment." (PMID 35604033, 2022). "DDX5 is a bona fide FL118 direct target and can act as a biomarker for predicting PDAC and CRC tumour sensitivity to FL118." (PMID 35604033, 2022). "Collectively, TRIM25 binds with DHX9 and DDX5 to participate in RNA processing to downregulate TCA enzyme expression, thereby remodeling the TCA cycle and glycolytic flux is increased to promote tumor proliferation." (PMID 36012594, 2022). "This review discusses the protein structure and biological functions of DDX5/DDX17 and explores their regulatory mechanisms in tumorigenesis and tumor progression, providing insights into their potential clinical application in tumor therapy." (PMID 35992805, 2022).
tumor (continued). "The exact mechanism of DDX5/DDX17 in tumorigenesis varies with tumor type and tumor development stage." (PMID 35992805, 2022). "This likely occurs through DDX5‐mediated transcription, which was demonstrated using the survivin gene as an example; and DDX5 appears to be a biomarker for reflecting PDAC and CRC tumour sensitivity to FL118 treatment." (PMID 35604033, 2022). "This review mainly discusses the molecular structure features and biological functions of DDX5/DDX17 and their effects on tumorigenesis and tumor progression, as well as their potential clinical application for tumor treatment." (PMID 35992805, 2022). "Many DEAD/H-box helicases, such as DDX3, DDX5, DDX10, and DDX21, have been reported to act both as oncogenes and tumor suppressors in different contexts." (PMID 36761420, 2022). "Our human tumour animal model studies further indicated that FL118 exhibits high efficacy to eliminate human PDAC and CRC tumours that have a high expression of DDX5, while FL118 exhibits less effectiveness in PDAC and CRC tumours with low DDX5 expression." (PMID 35604033, 2022). "Together, our studies have demonstrated that DDX5 is a bona fide FL118 target and biomarker for predicting PDAC and CRC tumour sensitivity to FL118 treatment." (PMID 35604033, 2022). "In our study, linc00473 promoted DDX5 expression by sponging miR-506, thus promoting CCA cell proliferation and invasion in vitro and CCA tumor growth in vivo." (PMID 32694946, 2020). "DDX5 and DDX17 contribute to tumor cell invasiveness by regulating alternative splicing of several DNA- and chromatin-binding factors." (PMID 32671031, 2020). "We observed significant over-expression of ADAR, ADARB1, DDX5/17/20, DGCR8, DICER1, DROSHA, EIF2C1-4 (AGO1-4), GEMIN4, POLR2A, TARBP2, TNRC6A and XPO5 in tumor tissue compared to adjacent mucosa." (PMID 31510013, 2019). "The overexpression of DDX5 in MCF-7 cells resulted in a significant increase in cell viability and a decrease in c-CASP3 levels, indicating that the overexpression of DDX5 reversed the antitumor effects of DOX and MA on tumor cells and led to a significant decrease in the anticancer effect." (PMID 39494326, 2024). "Notably, inhibition of Wnt/ β-catenin signaling or overexpression of DDX5 in a preclinical HCC model improved the anti-tumor efficacy of sorafenib, reducing tumor growth." (PMID 38036507, 2023). "Sorafenib significantly reduced DDX5 expression in vivo, but did not significantly affect tumor volume." (PMID 38036507, 2023). "Therefore, the posttranslational modification of DDX5/DDX17 is closely related to tumorigenesis and tumor progression, and in-depth research on the mechanisms of these actions will provide new ways to explore tumor pathogenesis and develop tumor therapies." (PMID 35992805, 2022). "Indeed, DDX5 and DDX17 also interact with multiple key tumor-promoting molecules and participate in tumorigenesis and tumor progression signaling pathways." (PMID 35992805, 2022). "Therefore, once DDX5/DDX17 expression is dysregulated, the cell signaling pathway will be disturbed, leading to tumorigenesis and tumor progression." (PMID 35992805, 2022). "For example, DDX5/DDX17 mediate the nuclear transport of β-catenin and promote the translocation of β-catenin from the cytoplasm to the nucleus, inducing tumorigenesis and tumor progression." (PMID 35992805, 2022). "Moreover, different posttranslational modifications, such as phosphorylation, acetylation, ubiquitination, and sumoylation, endow DDX5/DDX17 with different functions in tumorigenesis and tumor progression." (PMID 35992805, 2022). "When DDX5/DDX17 expression or their posttranslational modification is dysregulated, the normal cellular signaling network collapses, leading to many pathological states, including tumorigenesis and tumor development." (PMID 35992805, 2022).
tumor (continued). "DDX5, also among the top expressed DEG, is known to play a role in tumor cell proliferation and epithelial-mesenchymal transition in different malignancies and may therefore also represent a therapeutic approach for the treatment of pterygia." (PMID 35174178, 2021). "Additionally, DDX5 negatively correlated with p62/sequestosome 1 (SQSTM1) expression in HCC patients, and its expression was a biomarker in predicting prognosis after tumor resection." (PMID 33764710, 2021). "Furthermore, the ectopic expression of DDX5 and eEF1A2 also weakened the inhibitory effects of DRD2 on tumor proliferation as assessed by CCK8 and Transwell® assay." (PMID 33859743, 2021). "In addition, the expression of DDX5/20, DGCR8, DICER1, DROSHA, EIF2C1-4, GEMIN4, TNRC6A and XPO5 was deregulated not only in tumor tissue, but also in corresponding liver metastases compared to adjacent tissue." (PMID 31510013, 2019). "Once DDX5/DDX17 expression or DDX5/DDX17-related posttranslational modification is dysregulated, the cellular signaling network collapses or becomes abnormal, which leads to the acquisition of many pathological states, including those related to tumorigenesis and tumor development." (PMID 35992805, 2022). "DDX5 may represent a class of non-oncogenes with activity that is stimulated in the absence of key tumor suppressors." (PMID 35992805, 2022). "However, DDX5 is a highly active G4-resolvase that can effectively unfold the G4 structure and thus promote the transcription of the MYC gene to promote tumorigenesis and tumor progression." (PMID 35992805, 2022). "In addition, we found that DDX5 expression was significantly upregulated in tumor tissues compared to non-tumor groups, and increased in CRC cells (SW480, HCT-8, HT-29 and DLD-1) compared to NCM460 cells." (PMID 34234865, 2021). "Notably, DDX5 overexpression ( + Dox) did not affect tumor growth in the absence of sorafenib." (PMID 38036507, 2023). "Interestingly, DDX5, but not DDX17, affect key cellular pathways, including upregulation of AR in PCa and induction of epithelial-mesenchymal transition (EMT), a feature that is associated with tumor invasion capabilities." (PMID 31164793, 2019). "By contrast, xenograft tumors from Dox-fed animals treated with sorafenib exhibited sustained DDX5 protein levels, absence of GPX4 induction, and reduced tumor weight in comparison to those without Dox administration." (PMID 38036507, 2023).
infection (20 papers, 2011 to 2026). The state of being infected such as from the introduction of a foreign agent such as serum, vaccine, antigenic substance or organism. "Here, DDX5 was found to regulate inflammation caused by bacterial infection, indicating DDX5 may control diverse mechanisms in response to pathogenic infection." (PMID 38182816, 2024). "Growing evidence shows that DDX5 is implicated in the infection of several viruses." (PMID 29642538, 2018). "However, several studies have reported that the m6A modification affected the inflammatory response in different diseases; therefore, we further confirmed the specificity for DDX5-mediated m6A-modified regulation of inflammatory response in Mettl3 cKO mice after infection with pathogenic bacteria." (PMID 38182816, 2024). "While DDX3 indirectly modulates the host response to limit bacterial infection, DDX5 modulates host immunity in a fashion that must be fine‐tuned to allow for control of infection while preventing aberrant inflammation‐mediated tissue damage." (PMID 39620586, 2025). "To determine how DDX5 and DDX17 modulate KSHV lytic reactivation and infection, we wanted to assess the localization of DDX5 and DDX17 and determine if their localization is altered during lytic reactivation." (PMID 40257982, 2025). "Our data suggest systemic changes in the host during early infection, indicated by the altered expression of PRs, DDX5, BCL2, ANGPTL4, and other regulatory genes during early MDV infection." (PMID 39066292, 2024). "Dual depletion of YTHDF3 and DDX5 significantly lowered infection efficiency beyond single YTHDF3 depletion." (PMID 38649412, 2024). "Confocal microscopy analysis demonstrated that endogenous DDX5 co-localizes with the capsid protein in SINV-infected cells supporting the possibility that the two proteins interact upon infection." (PMID 38553727, 2024). "DDX5 synthesis exhibited an obvious decrease in MEFs during 0 ~ 6 h post-infection with S. aureus and P. multocida, as well as during 0-16 h post-infection with M. pneumoniae." (PMID 38182816, 2024). "Despite its modest overexpression, the presence of DDX5 was sufficient to partially rescue the GFP levels in a time course of SINV-GFP infection." (PMID 38553727, 2024). "It is thus conceivable that the cofactor DDX17 operates with DDX5 within the same complex, carrying out a synergistic or additive function during infection." (PMID 38553727, 2024). "To further investigate the innate immunity pathways regulated by DDX5, we detected the expression of p-TBK1, p-IKKγ, p-p65, and p-IRF7 in DDX5- or METTL3-knockdown or -overexpressing MEFs after infection with VSV." (PMID 33909701, 2021). "We found that the mRNA expression of IFN-β and IL-6, which are vital antiviral modulators of innate immune response, significantly increased in DDX5-knockdown MEFs at 6 and 12 h post-infection (hpi) with VSV." (PMID 33909701, 2021). "We quantified DoTT for two marker genes (SRSF3 and DDX5) by qRT-PCR upon infection of primary human fibroblasts with the respective mutant viruses." (PMID 31941886, 2020). "The opposite roles of DDX5 between DNA and RNA infection likely reflect the different modes of the biosynthesis of RNA and DNA viruses." (PMID 29642538, 2018). "Since there is a wave of lytic gene expression prior to establishment of latency during primary infection, the DDX5-17 proteins could be regulating RTA transcription and primary infection in a similar manner." (PMID 40257982, 2025). "Modeling of the DDX5–Nsp13 complex providesa plausible explanation for the synergic action of the two helicases,in a mechanism that is likely instrumental in the early stage of infection,when the concentration of Nsp13 is still low." (PMID 40821550, 2025). "In this study we demonstrate that DDX5 interacts with the SINV RNA during infection." (PMID 38553727, 2024).